LGALS9 (galectin 9)
Diseases named in the same sentence as LGALS9 in open-access papers (continued):
Sharing a sentence is not in itself a finding about the gene and the disease.
tumor (continued). "Here the authors show that co-expressed PD-1 protects TIM-3+ T cells from galectin-9-induced cell death and that anti-galectin-9 in combination with GITR agonism promotes an anti-tumor immune response." (PMID 33547304, 2021). "Protein expression of TIM-3 and its ligand, galectin-9, was quantified by digital imaging in 32 PCNSL patient tumor samples from a retrospective cohort we published recently 16 and in one postmortem normal brain sample." (PMID 33664848, 2021). "In these immunosuppressive marker genes, TGFB1, NECTIN2, LGALS9, LAG3, and IL10RB were significantly correlated with CCDC137 expression in most tumor types." (PMID 34055889, 2021). "For the purpose of investigating SUV39H1 mediated the costimulatory factors Tim-3 and galectin-9 expression through DNA methylation in vivo, we generated SiHa-SUV39H1 and HeLa-SUV39H1 tumor xenografts in nude mice." (PMID 32699524, 2020). "Especially CD4+ T cells showed a significant upregulation of galectin-9, whereas galectin-9 expression on CD8+ T cells increased only minimally within the tumor." (PMID 32055023, 2020). "To identify leukocyte subsets that express galectin-9 in PDAC, we performed flow cytometry on immune cells from tumor specimens and matched blood, freshly obtained from 12 PDAC patients undergoing surgery." (PMID 32055023, 2020). "As expected, compared to that of GL-261 WT tumor-bearing mouse CD8 + T cells, the antitumor immunity of GL-261 LGALS9−/− tumor-bearing mouse CD8 + T cells was enhanced, with an increased proportion of Ki67-positive cells and enhanced expression of IFN-γ/GzmB." (PMID 33093453, 2020). "TIM-3 interacts with numerous ligands including tumour-secreted galectin-9, high-mobility group protein B1 (HMGB1), carcinoembryonic antigen cell adhesion molecule 1 (CEACAM-1, expressed on tumour cells), and phosphatidyl serine (PtdSer)." (PMID 32645977, 2020). "The potential of galectin-9 as a novel therapeutic target in PDAC is important, considering reduced tumor growth in murine PDAC after galectin-9 blockade." (PMID 32055023, 2020). "Galectin-9 was highly expressed in human PDAC compared with normal pancreas and present on both tumor and immune cells." (PMID 32055023, 2020). "Further experiments showed that mice immunized with GL261 LGALS9−/− tumors still had sustained anticancer immune memory when they were inoculated with GL261 WT cells, which ultimately inhibited tumor growth and prolonged survival in the mice." (PMID 33093453, 2020). "In this study, we analyzed paraffin-embedded tumor tissue, freshly isolated immune cells from the tumor and peripheral blood, and serum of patients with PDAC for galectin-9." (PMID 32055023, 2020). "Tumor-infiltrating immune cells, especially CD3+ T cells, showed upregulation of galectin-9 compared with immune cells from matched blood." (PMID 32055023, 2020). "Namely, the presence of tumor infiltrating CD3+CD8+FoxP3− T cells, galectin-9+ dendritic cells (DC)/DC-like macrophages, a high CD14+CD163− (M1)/CD14+CD163+ (M2) macrophage ratio, and the expression of galectin-3 by tumor cells." (PMID 31248118, 2019). "Compared to non-tumor tissues (N), a variety of factors like TGF-β1, TGF-β2, HMGB1, PVR, nectin-2, galectin-9, PD-L1, PD-L2, and MICA/MICB were significantly higher in the tumor tissue (T)." (PMID 31234517, 2019). "Our results have confirmed that Tim-3 and galectin-9 are expressed mainly by tumor cells, since CD3 (a T cell biomarker) was barely detectable in tumor and undetectable in healthy tissue lysates." (PMID 31354733, 2019). "In our study, galectin-9 levels were positively correlated with those of the well-known oncogene EZH2 and were down-regulated by the tumor suppressor miR-22." (PMID 29316949, 2018). "We found that EZH2 and galectin-9 expression levels were up-regulated after IFN-γ stimulation in HCC, changes that we surmised are instrumental in modulating the tumor microenvironment." (PMID 29316949, 2018).
tumor (continued). "The ImmunoINTEL panels were complemented with drop-in IMR and IMR-L markers (PD1/PDL1, TIGIT/CD112-CD155, TIM-3/Galectin-9, SIRPa/CD47, LAG-3/HLADR) to profile the functional status of TILs, and to study the cytotoxic potential of tumor TILs." (PMID 30400835, 2018). "In recurrent NPC, to maintain immune escape, these high Galectin-9 expressing NPC cells maintains their ability to inactivate the survival and growth of tumour-infiltrating CD8+ lymphocytes." (PMID 28871094, 2017). "We used immunohistochemistry on tissue-microarrays to examine the co-expression of the immune inhibiting molecules PD-L1, Galectin-9, HVEM and IDO, as well as tumor CD8+ lymphocyte infiltration in HCC, in two independent cohorts of patients." (PMID 28344887, 2017). "TIM-3 blockade reduces galectin-9 driven apoptosis in tumor-infiltrating TIM-3+ CD8+ T cells and inhibits tumor growth in mice." (PMID 26493689, 2015). "Galectin-9/TIM-3 signaling blockade with anti-TIM-3 antibody reduces the apoptosis and in addition, inhibits tumor growth in mice." (PMID 26493689, 2015). "Interaction between tumor derived galectin-9 and TIM-3 on the infiltrating CD8+ T cells induce apoptosis in functionally active tumor-infiltrating TIM-3+CD8+ T cells." (PMID 26493689, 2015). "For example, tumor-derived extracellular vesicles are enriched in CD95L, TRAIL, or galectin 9, which can promote T cell apoptosis." (PMID 24978137, 2014). "To explore the potential effect of galectin-9 on Tim-3+ cells in tumors in situ, we examined the distribution of galectin-9 and Tim-3 in HCC tumor tissues using multi-color immunofluorescence and confocal microscopy." (PMID 23526963, 2013). "For stimulating effects, ICIs can induce an enhanced expression of tumor cell ISGs transcribing additional T-cell co-inhibitory ligands (e.g., TNFRSF14, LGALS9) where blockade of type I and II IFN signaling could reverse this effect and improve ICI responses." (PMID 39663510, 2025). "The high-response group exhibited elevated expressions of BTLA, LGALS9, PDCD1LG2, TIGIT, TNFSF15, and VTCN1 compared to the low-response group, suggesting that patients with this tumor profile may benefit from ICIs therapy." (PMID 40761787, 2025). "TIM-3 interacts with multiple ligands, such as Galectin-9, CEACAM1, phosphatidylserine (PtdSer), and HMGB1, promoting tumor immune tolerance and CD8+ T-cell exhaustion, thus facilitating tumor progression." (PMID 40552075, 2025). "Notably, however, the frequency of TNF-α, and IFN-γ producing T cells was increased for ABE-TILs upon co-culture with autologous tumor lines naturally expressing TIGIT or TIM3-specific ligands (i.e., CD112 and CD155 and galectin-9, respectively)." (PMID 41394272, 2025). "The interaction of TIM-3 with its ligands, like galectin-9, promotes T-cell apoptosis, and the formation of TIM-3/galectin-9/PD-1 lattices helps the survival of TIM-3+T cells, leading to the immunosuppressive tumor microenvironment (TME)." (PMID 41315319, 2025). "Furthermore, immune-suppressive factors such as galectin-9 (Gal9), mainly expressed on CD4+CD25+ regulatory T cells (Tregs) in OS, contribute to immune evasion and tumor progression." (PMID 40149640, 2025). "The inhibitory receptors expressed on T cells, interacting with their corresponding ligands expressed on antigen-presenting cells or tumor cells, such as PD-1/PD-L1, CTLA-4/CD86, TIM-3/Galectin-9, TIGIT/CD155, and BTLA/HVEM, play important roles in regulating T cell functions." (PMID 39329729, 2024). "As, Glutamine appears to play a prominent role in malignant tumor progression, especially in their myeloid group, therefore, in this study we aimed to evaluate the relation between TIM-3/Galectin-9 axis and glutamine metabolism in two types of AML cell lines, HL-60 and THP-1." (PMID 38267906, 2024).
tumor (continued). "Lack of mitofusin 1 reduced galectin-9 protein levels and strongly influenced immune cell recruitment and tumor development, highlighting the potential of mitochondria as a target in cancer treatment." (PMID 38195762, 2024). "Among these interactions, the Tim-3/Galectin-9 and TIM-3/Ceacam1 interactions result in similar downstream events because they bind to different regions in the IgV domain of Tim-3 and predominate in tumor cell immune escape mechanisms." (PMID 38927447, 2024). "The interaction between TIM3 and galectin 9 (Gal9) in CD8+ T cells leads to the reduction of the production of cytokines (IFNγ, IL-2, and TNFα), the inhibition of T cell proliferation, and the inhibition of anti-tumor immunity." (PMID 39372416, 2024). "Key tumour–non-cancerous cell interactions include the PD-L1/PD-1 (CD274/PDCD1) and Galectin-9/TIM-3 (LGALS9/HAVCR2) pathways, which are significantly upregulated in Low TPS and show a negative correlation with TPS, indicating the influence of the tumour microenvironment (TME)." (PMID 39457550, 2024). "Consequently, targeting LGALS9 and SPP1 within the microenvironment represents promising targets for remodelling anti‐tumour immunity." (PMID 39422697, 2024). "This system disrupts the Dectin-1-galectin-9 signaling axis in PDAC by reversing the immune-suppressive phenotype of TAMs, increasing the proportion of effector T cells in the tumor, and reducing Tregs, thereby inhibiting tumor progression." (PMID 39590166, 2024). "Previous studies have shown that EBV-infected NPCs released large amounts of exosomes containing LGALS9 (Galectin-9), which can interact with TIM-3 and induce apoptosis of TIM-3-expressing Th1 cells, leading to the escape of tumor cells from immune recognition." (PMID 37098551, 2023). "In addition, the interaction of LGALS9-HAVCR2, and ANXA1-FPR1 were also found between MRS1-tumor cells and MRS1-macrophages." (PMID 37543645, 2023). "Also, LGALS9, HBEGF, and GRN were confirmed to be over-expressed in macrophage subset, highlighting the potential roles in mediating tumor-macrophage interactions." (PMID 36864399, 2023). "Notably, TAMs had putative interactions with tumor‐infiltrating T cells through CD80/CD86‐CTLA4, PDL1/PDL2‐PD1, and LGALS9‐HAVCR2, suggesting their immunosuppressive capability on T cells." (PMID 37949673, 2023). "Galectin-9 expression in primary tumors was not significantly higher in tumor tissue compared to adjacent non-tumor tissue (p = 0.222)." (PMID 37047155, 2023). "Several immune checkpoint genes (HAVCR2, CD47, LGALS9, and CD276) were gradually upregulated along the DC differentiation trajectory, especially at the late stage, revealing that C3-DC might suppress tumor immunity." (PMID 36788228, 2023). "We previously identified that the glycan-binding protein Galectin-9 (Gal-9) has tumor-selective and non-apoptotic cytotoxicity towards various types of cancer, which depended on autophagy inhibition." (PMID 37407572, 2023). "However, some ICRs have been reported to be expressed on both T-cells and tumor cells, including V-domain immunoglobulin suppressor of T cell activation (VISTA), Galectin-9, and T-cell immunoglobulin mucin-3 (TIM-3)." (PMID 37970435, 2023). "Moreover, it was found that galectin-9 knockdown in tumor cells in PDAC enhanced the activity of T cells in the tumor microenvironment, and inhibited tumor growth." (PMID 36428567, 2022). "Interestingly, we found upregulation of galectin-9 (Lgals9), which supports the polarization of CD206+ macrophages (which are similar to the cells detected in ROC1 tumors) to support tumor growth." (PMID 35902768, 2022). "It has been shown that the interaction of TIM-3 expressed on DCs with an alternative HMGB1 ligand, rather than galectin-9, suppresses innate immunity in the tumor microenvironment." (PMID 36140182, 2022).
tumor (continued). "Similar results are obtained in ESCC; the mouse model also displays the proliferative role of Galectin-9 in ESCC, as its administration was also shown to inhibit tumor growth by inducing cell apoptosis via activating caspase-3, p38 mitogen-activated protein kinase, and JNK." (PMID 36358792, 2022). "Since the galectin-9/TIM-3 pathway is involved in producing CD4 + CD25 + regulatory T cells, exosomal galectin-9 may contribute to T-cell proliferation in the tumor and peripheral blood of NPC patients." (PMID 35565418, 2022). "Moreover, the positive correlations between CCDC137 expression and immunosuppressive genes, such as TGFB1, NECTIN2, LGALS9, LAG3, and IL10RB, indicate the key role of CCDC137 in regulating tumor immunology, macrophage polarization, and CAFs formation." (PMID 34055889, 2021). "As a result, most of the tumor cells expressed high levels of PD-L1 but not galectin-9 (Gal-9, a ligand for Tim3)." (PMID 34625113, 2021). "We found positive staining of tumor cells in IHC staining for VISTA in 2.1% (3/145), Galectin-9 in 36.6% (53/145), PD-L1 in 40.7% (59/145), CEACAM-1 in 57.2% (83/145), HVEM in 74.5% (108/145), PVR in 77.9% (113/145) and HLA-E in 84.8% (123/145) of patients 29–33." (PMID 34135436, 2021). "We found that tumor-infiltrating CD33high cells showed high gene expression levels of CD36, CD14, FUT4 (CD15), CD80, CD86, CSF1R and immune checkpoint ligand genes including CD274 (PD-L1), LGALS9 (galectin-9), PVR and VSIR." (PMID 33000418, 2021). "Recent studies have shown that galectin-9 promotes CD8 + T cell failure and induces proliferation of myeloid inhibitory cells by binding to T cell immunoglobulin mucin 3 (Tim-3), thereby participating in immune escape of tumor cells." (PMID 34093804, 2021). "Interestingly, we found exhausted CD4+ T cells expressed not only high levels of CD47 but also the ligand Galectin-9 in the TME of both plaque and tumor MF." (PMID 34885092, 2021). "The results showed that gender, age, total number of tumor involved regions, and the degree of surgical resection are not related to the expression of Galectin-9 and TIM-3." (PMID 34956239, 2021). "Furthermore, we correlated galectin-9 expression on blood CD4+, CD8+, and γδ T cells with tumor size, lymph node metastasis, and UICC stage." (PMID 32055023, 2020). "In line with our previous observations, levels of both Tim-3 and galectin-9 were substantially increased in tumour tissues compared to non-malignant samples." (PMID 33295886, 2020). "Patients with IPMNs did not have increased galectin-9 serum levels, suggesting galectin-9 to occur in a heterogeneous fashion with primary tumor growth." (PMID 32055023, 2020). "In order to further explore the relationship between HDACi resistance and immune checkpoint regulation, we measured the expression levels of mRNAs encoding the immune checkpoint molecules PD-L1, CTLA4, B7-1, B7-H3, B7x, VISTA, and Galectin-9, in both SAHA-responsive and -resistant tumor tissues." (PMID 32934224, 2020). "Few galectin-9 foci were detectable in tumor spheroids without small-molecule treatment, whereas all tested compounds induced formation of abundant galectin-9 foci." (PMID 32286269, 2020). "Activation of this pathway facilitated the translocation of galectin-9 onto the tumor cell surface, however no secretion of galectin-9 by tumor cells was observed." (PMID 31354733, 2019). "Unlike other galectins, galectin-9 both promotes and inhibits tumor activity, depending on its interactions with its ligands on T cells, antigen-presenting cells or tumor cells." (PMID 29389859, 2018). "Such patients displayed increased galectin-9-positive tumor cells and FOXP3+ lymphocytes, whereas the TIM-3+ lymphocytes were decreased in the tumor microenvironment compared with primary NPCs, suggesting that the galectin-9–TIM-3 pathway mediates immune escape by NPCs." (PMID 29389859, 2018).
tumor (continued). "Our second finding primarily focuses on the impact of immunologic markers in the tumour microenvironment, specifically how a low percentage of CD8+ lymphocytes, high percentage of Galectin-9+ NPC cells and high percentage of Foxp3+ lymphocytes affect the outcome of recurrent NPC." (PMID 28871094, 2017). "Tumour transcriptional analysis demonstrated that, as a rapid and early consequence of vaccination, several profoundly immunosuppressive genes were highly upregulated, including CD274 (PD-L1), LGALS9 (Galectin-9), TGFβ1, LAG3 and HAVCR2 (TIM-3)." (PMID 26861383, 2016). "Cells expressing galectin-9 were generally not abundant in either the tumor epithelium or the stromal cells." (PMID 26066796, 2015). "Additionally, Tim-3+ Tregs specifically accumulated in the tumor nest, where Tim-3+ CD4 cells had close contact with the Tim-3 ligand galectin-9." (PMID 23526963, 2013). "Noticeably, we did not detect the expression of galectin 9 on the tumor cells in spite of the immune enhancing effect of the anti-TIM3 mAb." (PMID 24044888, 2013). "Both the tumor-infiltrating CD4+ cells and macrophages expressed abundant levels of galectin-9." (PMID 23526963, 2013). "Keeping in mind the immunosuppressive functions of galectin-9, it will be interesting to know whether relative galectin-9 abundance will be predictive of NPC tumor response to various therapeutic modalities especially adoptive immunotherapy." (PMID 22805533, 2012). "This association was potentially attributed to MFSD12’s dual roles: promoting tumor cell proliferation, migration, and metastasis while critically modulating the tumor immune microenvironment, particularly through interaction with the HAVCR2/LGALS9 immune checkpoint axis." (PMID 41194934, 2025). "Together with the decreases in Tim-3 and CX3CR1 levels in pNK cells after interaction with MCF-7 spheroids, these findings may indicate the involvement of the Tim-3/galectin-9 and CX3CR1/CX3CL1 pathways in the regulation of the cytotoxic response of pNK cells to MCF-7 tumor cells in the 3D model." (PMID 39457710, 2024). "Furthermore, elevated galectin-9 levels were detected in tumor-infiltrating T lymphocytes from non-responders to anti-programmed death-1 (PD-1) therapy compared with those from the responders." (PMID 36873388, 2023). "Similarly, galectin-9 also acts as a competitive inhibitor by blocking the VCAM1-α4β1 interactions, thereby reducing tumor cell adhesion to the vascular endothelium and consequent tumor cell extravasation and metastasis." (PMID 36873388, 2023). "From 10 immune checkpoint proteins, galectin-9 and OX40L had the higher relative contribution to OS (33.55%) and RFS (29.02%), respectively, while the percentage of positive tumor cells and the distance between positive TILs and positive tumor cells contributed the most to predict OS." (PMID 37568797, 2023). "For example, exosomes derived from cancer cells containing FasL, TGF-β, NKG2D ligand, Galectin-9, HSP72 and/or other immunomodulatory factors support the immune escape of tumor cells and induce the differentiation of monocyte cell lines that support the tumor cell phenotype." (PMID 35906674, 2022). "Using multiplex chromogenic immunohistochemistry and stereological-based cell counting, they found that the majority of the TIM-3+ or galectin-9+ cells corresponded to TAMs rather than tumor cells, and that the sparse TIM-3+ TILs preferentially interacted with galectin-9+ TAMs." (PMID 35008740, 2021). "Also, interactions such as CD80-CTLA4, CD86-CTLA4, and LGALS9-HAVCR2, were mostly enriched in tumor, implying that these interactions might jointly conduce to immune escape." (PMID 33298893, 2020). "Serum levels of galectin-9 were increased independently of tumor stage, indicating that galectin-9 may not generally reflect tumor progression." (PMID 32055023, 2020). "No hypermethylation pattern related to low LGALS9 expression was identified in tumour cells." (PMID 32902187, 2020).